CASP4 (caspase 4)
Diseases named in the same sentence as CASP4 in open-access papers (continued):
Sharing a sentence is not in itself a finding about the gene and the disease.
pneumonia (2 papers, 2022 to 2023). An acute, acute and chronic, or chronic inflammation focally or diffusely affecting the lung parenchyma, caused by an infection in one or both of the lungs (by bacteria, viruses, fungi, or mycoplasma.). "We found that caspase-4 and caspase-5 mRNA levels significantly upregulated in the PBMCs of pneumonia patients with severe phenotype, while they slightly increased in non-severe patients compared to healthy controls, and increased in BALF of severe cases compared with the non-severe group." (PMID 37180156, 2023).
prostate carcinoma (2 papers, 2022 to 2023). A carcinoma that arises from epithelial cells of the prostate gland. "Some studies suggested that pyroptosis is involved in abnormal changes in signalling pathways in prostate cancer; the main pyroptosis pathways related to prostate cancer are the Caspase-1 pathway, Caspase-4/5/11 pathway and Caspase-3 signalling pathway." (PMID 36702978, 2023). "In prostate cancer cells, changes in the structure of the endoplasmic reticulum lead to an increase in expression of Caspase-4, which in turn induces programmed cell death." (PMID 36702978, 2023). "Additionally, in vitro experiments have suggested that cardiotonic glycosides might diminish the stability of prostate cancer cells, induce an increase in Caspase-4 expression, and promote pyroptosis." (PMID 36702978, 2023).
tuberculosis (2 papers, 2018 to 2022). A chronic, recurrent infection caused by the bacterium Mycobacterium tuberculosis. "Therefore, ASTA inhibits inflammation-induced pyroptosis by inhibiting the caspase 4/11-gasdermin D pathway and has the potential to protect lung tissue from tuberculosis-related inflammatory injury." (PMID 36523416, 2022). "Caspase-4 quantification was also assessed in the lung tumor mass of 98 paired NSCLC patients compared to 10 non-tumor lung tissues (i.e. tuberculosis)." (PMID 29721208, 2018).
vitiligo (2 papers, 2022). Generalized well circumscribed patches of leukoderma that are generally distributed over symmetric body locations and is due to autoimmune destruction of melanocytes. "Further analysis of melanocytes revealed strong pyroptosis responses existed in patients with vitiligo.Results demonstrated that CASP1, CASP4, CASP6, CASP8, and GSDMD expression was significantly upregulated in melanocytes of patients with vitiligo." (PMID 35962439, 2022).
age-related macular degeneration (1 paper, 2025). Age-related loss of vision in the central portion of the retina (macula), secondary to retinal degeneration. "In age-related macular degeneration (AMD), degeneration of the retinal pigment epithelium (RPE) in macular lesions is driven by a caspase-4-mediated atypical inflammasome pathway." (PMID 39994107, 2025).
alcoholic hepatitis (1 paper, 2022). Acute hepatitis resulting from ingestion of alcohol. "CASP4 and IL-18 are both involved in the pathogenesis of alcoholic hepatitis (AH) but has opposite effects in the pathogenesis." (PMID 35785176, 2022).
amyloid (1 paper, 2025). "To investigate the role of caspase-4 in the development of amyloid-related pathologies induced by P. gingivalis-LPS, we used SH-SY5Y cells due to the absence of detectable release of Aβ1–42 and Aβ1–40 peptides in P. gingivalis-LPS-transfected HMC3 microglial cells." (PMID 40497980, 2025).
cholestasis (1 paper, 2024). Impairment of the bile flow caused by obstruction within the liver, or outside the liver in the bile duct system. "Since BA metabolites can induce the expression of lncRNA57RIK, which determines the interaction of GBPs and caspase-4/11 upon exposure to LPS, this might also provide an explanation for excessive inflammation observed in patients with cholestasis." (PMID 39664579, 2024).
chronic lymphocytic leukaemia (1 paper, 2018). "We found that the circulating caspase-4 was significantly lower in chronic lymphocytic leukaemia (CLL, n = 12), non-Hodgkin lymphoma (NHL, n = 12) and multiple myeloma (MM, n = 12)." (PMID 29721208, 2018).
Cirrhosis (1 paper, 2024). A chronic disorder of the liver in which liver tissue becomes scarred and is partially replaced by regenerative nodules and fibrotic tissue resulting in loss of liver function. "Mechanistically, our current findings suggest that the sterile inflammatory milieu in cirrhosis promotes caspase-4-dependent activation of neutrophil-GSDMD, which leads to NETs generation in the thrombus and liver." (PMID 39201786, 2024). "We found that the expression of full-length and processed caspase-4 was also significantly higher in neutrophils from the individuals with cirrhosis with LPS incubation." (PMID 39201786, 2024).
colon adenocarcinoma (1 paper, 2022). "The somatic mutation of eight risk PRGs (CASP4, GPX4, GSDMC, TLR3, NLRP1, PLCG1, IL18, and IRF1) hardly occurred in PAAD samples but were commonly observed in colon adenocarcinoma (COAD) and stomach adenocarcinoma (STAD) ones." (PMID 35000541, 2022).
colorectal polyp (1 paper, 2025). "Next, the expression of caspase-4 in the histological subtypes of colorectal polyp (Table A2) were assessed, to determine the disease context and progression stage at which caspase-4 becomes elevated." (PMID 39866724, 2025). "Differentiating high from low grade dysplasia in colorectal polyps can be challenging for histologists, therefore this result suggests that caspase-4 staining may increase the ability to distinguish a focus of HGD or T1CRC from the surrounding LGD of a polyp." (PMID 39866724, 2025).
coronary atherosclerosis (1 paper, 2021). Atherosclerosis of the coronary vasculature. "The level of caspase-4 mRNA expression in PBMCs was positively correlated with the severity of coronary atherosclerosis, which was indicated by the SYNTAX score." (PMID 33981234, 2021).
coronary heart disease (1 paper, 2021). "Consistently, the mRNA expression of caspase-4 and gasdermin D was upregulated in peripheral blood mononuclear cells from patients with coronary heart disease." (PMID 33981234, 2021).
cyst (1 paper, 2016). A sac-like closed membranous structure that may be empty or contain fluid or amorphous material. "Thus, all the caspase genes examined were enhanced in the AQP11(−/−) kidney before (at two weeks) and after (at eight weeks) cyst formation with remarkably higher expressions of Casp1, Casp4 and Casp12." (PMID 27916883, 2016).
diabetic kidney disease (1 paper, 2023). Progressive kidney disorder caused by vascular damage to the glomerular capillaries, in patients with diabetes mellitus. "Decreased ATP Binding Cassette Transporter A1 (ABCA1) expression and caspase-4-mediated noncanonical inflammasome contribution have been described in podocytes in diabetic kidney disease (DKD)." (PMID 37316538, 2023).
dysplasia (1 paper, 2025). A usually neoplastic transformation of the cell, associated with altered architectural tissue patterns. "This study demonstrates that epithelial caspase-4 is selectively expressed in colon tissue during the development of dysplasia." (PMID 39866724, 2025). "In the sCRC pathway, caspase-4 is expressed in the epithelial and stromal tissue of all histological subtypes of colonic polyps, with a significant increase in epithelial expression from low-grade dysplasia to high-grade dysplasia progression." (PMID 39866724, 2025).
E. coli infection (1 paper, 2018). "Our findings indicate that E. coli infection activates caspase-4, subsequently resulting in cell pyroptosis and maturation of IL-1β and IL-18 via an NLRP3 inflammasome-dependent and ASC-independent pathway." (PMID 30087667, 2018). "At 3 h after E. coli infection, expression of cleaved caspase-4 (26 kDa) in WT and ASC-/- cells pre-incubated with L. rhamnosus GR-1 was lower than in untreated control cells and cells only infected with E. coli." (PMID 30087667, 2018). "Lactobacillus rhamnosus GR-1 suppresses ASC-dependent NLRP3 inflammasome activation and ASC-independent caspase-1 processing by inhibiting caspase-4 activation, thereby attenuating cell pyroptosis and cytokine production and thus preventing establishment of E. coli infection." (PMID 30087667, 2018).
endometritis (1 paper, 2022). An acute or chronic, usually bacterial infectious process affecting the endometrium. "According to immunohistochemistry, the expression of caspase-1 in endometritis tissues was increased by sixfold compared to the healthy group, and the expression of caspase-4 was found to increase by sevenfold compared to the healthy group." (PMID 36430491, 2022). "We speculate that caspase 4 may be activated by NETs during endometritis and cleave pro-IL-1β, pro-IL-18, and GSDMD to induce pyroptosis." (PMID 36430491, 2022). "Qualitative and quantitative analysis of major pyroptosis-related proteins (caspase-1, caspase-4, ASC, GSDMD-N, and NLRP3) in endometrial tissues showed that pyroptosis occurred in endometrial tissues of cows with endometritis." (PMID 36430491, 2022).
endophthalmitis (1 paper, 2021). An infectious process affecting the internal structures of the eye. "Additionally, genes encoding pro- and antiapoptotic/pyroptosis molecules were found to be differentially regulated in MDR-PA-induced endophthalmitis and included upregulation of caspase-1, caspase-4, and caspase-8." (PMID 35046947, 2021).
endotoxemia (1 paper, 2020). "TLR4 had been considered a gatekeeper of LPS-induced lethality (endotoxemia) and E. coli-induced septic shock, but the non-canonical inflammasome, mediated by caspase-11 in mice or caspase-4/5 in humans, is newly defined as the gatekeeper for the sepsis." (PMID 33154451, 2020).
gastric tumors (1 paper, 2023). "Our results confirmed that the expression of GPX4, CASP6, IL-6, CASP5, CASP4, and TIRAP was greatly up-regulated in gastric tumors relative to normal tissues." (PMID 37595258, 2023).
Gram-negative pneumonia (1 paper, 2018). "In a mouse model of Gram-negative pneumonia, deletion of caspases -2 and -11, the mouse orthologue of caspase-4, reduced pulmonary inflammation, immune cell infiltration and lung damage." (PMID 29643440, 2018).
head and neck squamous cell carcinoma (1 paper, 2023). A squamous cell carcinoma that arises from any of the following anatomic sites: lip and oral cavity, nasal cavity, paranasal sinuses, pharynx, larynx, and salivary glands. "Alternatively, few studies have reported the loss and downregulation of CASP4 was associated with poor prognosis in head and neck squamous cell carcinoma." (PMID 37245006, 2023).
hyperlipidemia (1 paper, 2024). "Taken together, our results have demonstrated that hyperlipidemia and CKD significantly increase the plasma LDL-VLDL level and cytosolic LPS levels in the aorta; activate CASP4/11 more than CASP1; and increase 7 secretome cytokines and chemokines in plasma." (PMID 39024553, 2024).
intestinal infection (1 paper, 2018). "Caspase-11 is the murine ortholog of human caspase-4, which was reported to mediate IL-18 secretion and enterocyte pyroptosis during intestinal infection." (PMID 30138458, 2018).
keratitis (1 paper, 2021). A corneal disease that is characterized by inflammation of the cornea. "The study indicated the involvement of non-canonical pyroptosis in P. aeruginosa keratitis, and the expression of caspase-4/5/11 and cleaved GSDMD in LPS-induced cell models, keratitis rat models, and P. aeruginosa keratitis patients was increased." (PMID 34925047, 2021).
kidney tumors (1 paper, 2020). "CASP4 is over-expressed in kidney tumors, with fold change 2.697-fold to normal kidney." (PMID 32003756, 2020).
leishmaniasis (1 paper, 2023). Infectious disease that is transmitted through the bite of hematophagous female phlebotomine sand flies. "Still, our data demonstrated an overall increased expression of inflammasome-related genes such as Gsdmd, Nlrp3, Casp1, Casp4, Il1b, Ifng, Tnfa, Il10, and Il17a when we compared Leishmaniasis patients with controls." (PMID 36828815, 2023).
liver cirrhosis (1 paper, 2023). "To understand if differential regulation of CASP4 versus CASP5 was specific to Gram-negative sepsis or general to severe infections with immunosuppression, we studied a cohort of patients with liver cirrhosis and acute decompensation and ascites." (PMID 38106412, 2023).
lymphopenia (1 paper, 2023). Reduction in the number of lymphocytes. "Our present results strongly suggest that down-regulation of caspase-4 against a background of low IFN signaling, as prevalent in lymphopenia, may be a major cause of inflammasome dysfunction and innate immunosuppression in human severe infections." (PMID 38106412, 2023).
malaria (1 paper, 2021). Malaria is a serious and sometimes fatal disease caused by a parasite that commonly infects a certain type of mosquito which feeds on humans. "The work of Gazzinelli’s group used genetic and molecular approaches to demonstrate that CASP-8, CASP-1, mouse CASP-11, and its human ortholog CASP-4 were upregulated in monocytes from malaria patients and mice malaria models." (PMID 33672278, 2021).
malignant mesothelioma (1 paper, 2023). A malignant neoplasm of the pleura or peritoneum, arising from mesothelial cells. "γ-tocotrienol induced malignant mesothelioma cell death with the increase in CHOP, Grp78, and caspase-4 mRNA levels." (PMID 37111076, 2023).
mesothelioma (1 paper, 2023). A usually malignant and aggressive neoplasm of the mesothelium which is often associated with exposure to asbestos. "While raptinal induced clear caspase 3 and GasE activation, terfenadine was not successful for caspase 4 and GasD in the mesothelioma cell lines." (PMID 38077396, 2023).
myocardial diseases (1 paper, 2023). "Although the involvement of the caspase-4 inflammasome in myocardial diseases such as myocardial reperfusion-induced microvascular injury has been reported, the roles of the caspase-4 inflammasome and the caspase-5 inflammasome in VMC have not been established and need more exploration." (PMID 37256114, 2023).
Obesity (1 paper, 2025). Accumulation of substantial excess body fat. "Lipopolysaccharide (LPS, endotoxin) -mediated signaling of caspase-4 (human) and -11 (rodent) can induce the maturation of inflammatory cytokine IL-1β and cell pyroptosis, which is associated with the pathophysiology of many diseases such as obesity." (PMID 40356927, 2025). "Mechanistic ally, the binding of caspase 4/11 to LPS requires lncRNARIK to cause activation of the caspase 4/11 complex, which ultimately caused inflammation to promote sensitivity to high fat diet (HFD) -mediated obesity." (PMID 40356927, 2025).
periodontal disease (1 paper, 2025). "Notably, TGF-α levels are significantly reduced in patients with periodontal disease, supporting the notion that caspase-4 regulates epithelial responses in disease progression." (PMID 40137780, 2025).
polyp (1 paper, 2025). A usually exophytic mass attached to the underlying tissue by a broad base or a thin stalk. "In the sCRC pathway, all histological polyp subtypes examined were found to express caspase-4 in both epithelial and stromal compartments, with significantly increased epithelial expression upon LGD to HGD progression." (PMID 39866724, 2025). "In the stroma, caspase-4 expression was evident across all polyp subtypes, consistent with an inflamed microenvironment." (PMID 39866724, 2025).
rectal cancer (1 paper, 2023). A primary or metastatic malignant neoplasm that affects the rectum. "Therefore, further investigation of these SNPs in CASP4 is required to determine the function in rectal cancer." (PMID 37144561, 2023).
renal carcinoma (1 paper, 2022). A carcinoma arising from the epithelium of the renal parenchyma or the renal pelvis. "Interestingly, evidence indicated that elevated expression of CASP4 was associated with poor survival in patients with renal cancer." (PMID 36196256, 2022).
rheumatic diseases (1 paper, 2024). "In conclusion, the mouse caspase-11 (and possibly human caspase-4) non-canonical inflammasome plays regulatory roles in the pathogenesis and progression of various types of rheumatic diseases in functional association with other cellular factors." (PMID 38396768, 2024).
sepsis syndrome (1 paper, 2020). "Juxtapose, in the conditions of unresolved inflammation, TLR4 and caspase-4/11 activation can result in the amplified innate immune signaling, systemic overexpression of the pro-inflammatory mediators and pyroptosis which prompts the onset of sepsis syndrome and a fatal septic shock." (PMID 33329561, 2020).
squamous carcinoma (1 paper, 2020). "ROC analyses showed that the detection of caspase-4 in lung tumor masses was an excellent diagnostic tool for both adenocarcinoma (red line) and squamous carcinoma (red line) compared to caspase-5 (green line)." (PMID 33187551, 2020). "Caspase-4 positive adenocarcinoma (79.3%) and squamous carcinoma (88.2%) patients had lower median survival than patients who had lower levels of caspase-4." (PMID 33187551, 2020). "In this pattern we analyzed positive correlation between CASP4 and other genes according to Spearman correlation coefficient > 0.25 taking into consideration both adenocarcinoma and squamous carcinoma patients reported in the database." (PMID 33187551, 2020).
staphylococcus aureus infection (1 paper, 2022). An infectious process in which the bacteria Staphylococcus aureus is present. "The KEGG analysis revealed that CASP4-co-expressed genes were enriched in phagosomes, Epstein–Barr virus (EBV) infection, allograft rejection, viral myocarditis, and Staphylococcus aureus infection." (PMID 36713560, 2022).
steatosis (1 paper, 2015). Increased lipid within the cytoplasm of cells. "The analysis of the mRNA levels showed a significant increase in both the deleterious [Chop/Grp78] ratio (54-fold increase), and inflammasome components (caspase-4, caspase-1 and IL-1β) in NASH patients (n=9) compared with patients without NAFLD (n=6) and with steatosis (n=15)." (PMID 26355342, 2015).
Stroke (1 paper, 2024). Sudden impairment of blood flow to a part of the brain due to occlusion or rupture of an artery to the brain. "Male MMP-3 KO stroke brains also exhibited downregulation of apoptosis-related genes such as Casp9, Casp7, Bmf, Casp1, Bid, Casp6, Casp3, Casp2, Fas, Casp4, and Casp8." (PMID 39000490, 2024).
subarachnoid hemorrhage (1 paper, 2019). A serious neurological disorder characterized by intracranial hemorrhage into the subarachnoid space. "Other greenyellow hubs were associated with endothelin-1 signaling (PLBD1, MAPK14, CASP4), which is implicated in cerebral vasospasm following subarachnoid hemorrhage." (PMID 30836997, 2019).
testicular hydrocele (1 paper, 2023). Accumulation of serous fluid between the layers of membrane (tunica vaginalis) covering the TESTIS in the SCROTUM. "The testis cell pyroptosis mediated by CASP1 and CASP4 found in this study was limited to the testicular tissue of patients with SCOS, possibly caused by known factors, such as varicocele, testicular microlithiasis, and testicular hydrocele or other unknown factors." (PMID 37296437, 2023).
triple-negative breast carcinoma (1 paper, 2025). An invasive breast carcinoma which is negative for expression of estrogen receptor (ER), progesterone receptor (PR), and human epidermal growth factor receptor 2 (HER2). "The article by Adinew and colleagues, in which integrated bioinformatics methods were used as a research method, showed a reduced level of expression of the CASP4 gene in patients with triple-negative breast cancer." (PMID 40806590, 2025).
type 2 diabetes (1 paper, 2020). "In human monocytes, CASP5 and CASP4 could be activated by saturated fatty acids, then trigger IL‐1β and IL‐18 release, which contributed to type 2 diabetes." (PMID 32311223, 2020).
Yersinia infection (1 paper, 2023). "Whether caspase-8 and caspase-1 are activated downstream of caspase-4 or are acting in a parallel pathway during Yersinia infection of human IECs is unknown." (PMID 37615436, 2023).